BRAF (B-Raf proto-oncogene, serine/threonine kinase)
Diseases named in the same sentence as BRAF in open-access papers (continued):
Sharing a sentence is not in itself a finding about the gene and the disease.
tumor (continued). "According to the data from the cancer genome atlas, PTC has been classified as a MAPK driven tumor with two significant signaling drivers—mutated BRAF and RAS." (PMID 33669363, 2021). "These tumors also harboured distinct EGFR 19Del versus BRAF V601E driver mutations plus multiple unique non-synonymous mutations in each tumor, resulting in a high-probability classification of MPLC with coincidental TERT Amplification." (PMID 34109114, 2021). "Tumours with the BRAF V600E mutation can grow at any location in the CNS, and over 33% occur in the midline of the brain." (PMID 33557011, 2021). "Of note, this discrepancy was largely due to insufficient neoplastic tissue in the sample, most likely resulting from the fact that BRAF-mutant tumors are generally associated with mucinous adenocarcinoma that contain fewer tumor cells." (PMID 34259881, 2021). "On a subset of CRC patients, we compared the mutation status on KRAS (G12A, G12D, G12V, G13D) and BRAF (V600E) genes in the primary tumor and cfDNA isolated from the serum." (PMID 33669856, 2021). "Patients whose tumor harbored NRAS mutations or that coexpressed also BRAF mutations were excluded from this retrospective analysis." (PMID 34660299, 2021). "This stresses the need for further stratification and patient selection beyond RAS/BRAF mutations and tumour sidedness." (PMID 34253874, 2021). "An observed predominant activation of FRMD5 in BRAF-mutated specimens was tested in BRAF V600E tumor samples using Western blot analysis." (PMID 34201607, 2021). "Combination treatment with oHSV and MEKi Trametinib enhanced virus replication mediated by down-regulation of STAT1 and PKR expression or phosphorylation in BRAF V600E-mutated tumor cells as well as BRAF wt/KRAS-mutated tumor cells." (PMID 34578339, 2021). "It is essentially a dual tumor with a component of classical PTC with malignant epithelial proliferation (BRAF-mutated) and another component of mesenchymal proliferation (CTNNB1-mutated)." (PMID 34503292, 2021). "Then, the oHSV replication and tumor cell killing were investigated in both BRAF wild type (wt) (Caco-2 cell) and V600E-mutated tumor cells (Widr and HT29 cells)." (PMID 34578339, 2021). "We successfully determined BRAF mutational status in all primary tumor samples as compared to gold standard pathology." (PMID 33799709, 2021). "Studies reveal that PI3CG, the gamma subunit of PI3K and BRAF mutations determine tumor formation and progression due to their active involvement of the RAS genes." (PMID 37305163, 2021). "Similar results were found in patients from the GEO cohort; BRAF mutated patients were more likely to be female (p = 0.0018), older (p < 0.0001), and had the tumor at the right colon (p < 0.0001)." (PMID 34381786, 2021). "Conversely, inhibition of BRAF (BRAFi) is associated with significant immunological changes in the tumor microenvironment that are generally considered favorable for anti-tumor immunity." (PMID 34025662, 2021). "The eligibility for BRAF pathway-targeted therapy is predicated on the detection of a BRAFV600 mutation in the tumor." (PMID 34298804, 2021). "The high expression of CAF markers, such as platelet-derived growth factor (PDGFR)-β, α-smooth muscle actin (α-SMA), and vimentin in tumor tissue, was associated with lymph node metastasis, BRAF V600E mutation, and shorter survival in PTC." (PMID 35008368, 2021). "In summary, CLNM occurred in 38.0% of cN0 adult PTC patients undergoing PCLND; multivariate logistic regression analysis revealed age, tumor bilaterality, lymphovascular invasion and BRAF mutations as independent risk factors for CLNM in adult PTC patients." (PMID 35111686, 2021). "BRAF appears to act through the dentate/methylating pathway and, indeed, BRAF-mutant tumors are characterized by the methylation of CpG islands that cause the epigenetic repression of tumor suppressor genes, known as CpG island methylating phenotype tumors." (PMID 34988329, 2021).
tumor (continued). "Before taking Cotellic in combination with vemurafenib, patients must have BRAF V600 mutationpositive tumour status confirmed by a validated test." (PMID 34790681, 2021). "The BRAF V600E mutation is of particular interest in neoplasia, as BRAF mutations can result in constitutive activation of the MAPK signaling pathway and contribute to uncontrolled cell proliferation." (PMID 33799709, 2021). "Since this approach has significantly improved overall survival, assessment of BRAF mutational status in tumor tissue, with standardized molecular methods, is crucial for treatment decisions." (PMID 33954019, 2021). "Intriguingly, recent reports show that activation of AhR has been associated with resistance to BRAF-inhibitors and tumor dormancy in melanoma." (PMID 33446631, 2021). "It should be noted that the tumor was positive for BRAF p.V600E (VAF = 15%) and TERT C228T mutations and was reclassified in the ATA high risk category at the last follow-up." (PMID 33821390, 2021). "BRAF mutation status was either determined on the primary tumor (N = 20), local recurrence (N = 3), or metastasis (N = 79)." (PMID 33915880, 2021). "CRC development is driven by Wnt/Myc hyperactivation, KRAS/BRAF mutation, genetic instability and accompanied by progressive immunosuppressive tumor microenvironment (TME)." (PMID 34221955, 2021). "The effects of NRAS/BRAF mutation on the tumor microenvironment need to be evaluated in future studies using larger cohorts." (PMID 34272423, 2021). "Our single-cell analysis revealed that BRAF V600E mutation tumor epithelial cells highly expressed TACSTD2 and CLDN3, which were then validated in TCGA data." (PMID 34805166, 2021). "To assess the independent predictive value of PDCD4 expression in tumor and stroma, we performed Cox proportional hazards analysis, which included as covariates treatment information and BRAF/NRAS mutational status." (PMID 33801444, 2021). "In a pan-cancer study, it was noted that BRAF has a higher rate of specific driver mutations in leukocytes of cancer patients, a phenomenon associated with tumor-immune cell interactions." (PMID 34993195, 2021). "The synthetic lethal effect of PTPN11 loss with BRAF inhibition was then confirmed in vivo, in a xenograft model where tumor growth was almost completely suppressed." (PMID 34065438, 2021). "Of 20 patients with isolated CRC‐PM, 11 (55%) had a KRAS or BRAF tumor tissue mutation and were selected for cfDNA analysis." (PMID 33635598, 2021). "We compared the different clinicopathological characteristics, including age, gender, tumor size, BRAF V600E mutations, and histological types among the six diagnostic categories proposed by TBSRTC in this study." (PMID 34664843, 2021). "These targeted therapies can have impressive initial efficacy in tumours driven by BRAF V600 mutations." (PMID 33549048, 2021). "The therapy restored radioiodine accumulation in BRAF-mutated patients and led to tumor control in 90% of cases." (PMID 34769260, 2021). "Firstly, the BRAF mutation status was often determined on other tumor tissue than the segmented lung metastases." (PMID 33915880, 2021). "Regarding the pathogenesis of AM, BRAF mutation is found in approximately 60–80 % of this tumor and believed to play an essential role in its tumorigenesis." (PMID 34261507, 2021). "MEK inhibitors have shown potential efficacy in cancers with MEK or BRAF mutations, especially in BRAF V600E mutant tumour cell lines." (PMID 34012925, 2021). "In a subset of patients, we compared the mutation status of KRAS and BRAF genes in the primary tumor and serum samples." (PMID 33669856, 2021). "Studies have shown that BRAF V600E mutation was associated with large tumor size, thyroid capsule invasion, extraglandular invasion, lymph node metastasis, and high AJCC stage in PTC patients." (PMID 34926235, 2021).
tumor (continued). "Since then it has been reported that while targeting multiple components of the RAF–MEK–ERK pathway yield initial tumor regression in most patients with BRAF(V600E) mutation, resistance often still occurs." (PMID 34874009, 2021). "Adaptive resistance mechanisms are acquired by tumour cells to compensate for the loss of BRAF signalling in response to BRAF inhibitors." (PMID 34066022, 2021). "BRAF mutated tumor had higher stromal score (p = 0.0041), immune score (p < 0.0001), ESTIMATE score (p < 0.0001), and lower tumor purity (p < 0.0001)." (PMID 34381786, 2021). "Patient 4 was initially diagnosed with a primary tumor that had the BRAF V600E mutation and underwent treatment with FOLFIRI plus cetuximab as the first-line chemotherapy." (PMID 34840814, 2021). "KRAS and BRAF mutation status in plasma cfDNA are highly correlated with mutation status in tumor tissue." (PMID 34070592, 2021). "Dabrafenib is a BRAF inhibitor and has a good anti-tumor effect in BRAFV600E mutated cancer, whereas MEK inhibitor trametinib can enhance the inhibitory effect of BRAF." (PMID 34925209, 2021). "A meta-analysis, including 3,437 patients, showed that the BRAF V600E mutation was correlated with some aggressive clinicopathological features, such as tumor multifocality, extrathyroidal extension, lymph node metastases, and advanced stage of PTMC." (PMID 35002954, 2021). "The mutations involving the GTP-ase RAS protein family and its downstream BRAF lead to loss of cell cycle regulation at key checkpoints, which are the main driver mutations for several tumor types, e.g., colorectal carcinogenesis." (PMID 34578339, 2021). "It is likely that MAPK1/3 activation in the presence of CRAF allows tumor cells to maintain metabolism and growth in certain cell line mutations, allowing resistance to BRAF inhibition." (PMID 34831420, 2021). "The efficiency of anti-EGFR depends on the KRAS/BRAF mutation status, as it was demonstrated that BRAF-mutated tumours had reduced response rates to anti-EGFR, even though they were KRAS wild-type." (PMID 34945008, 2021). "We identify BRAF and MYC as key mediators of KRAS-driven tumor immune suppression and show that loss of BRAF effectively blocks tumor growth in mice." (PMID 33674596, 2021). "In our studies, therapeutic effectiveness was seen in syngeneic tumor mice with BRAF wt/KRAS-mutations." (PMID 34578339, 2021). "None of the other patients exhibited liquid biopsy mutations, except one, with a BRAF mutation confirmed in primary tumor and peritoneal dissemination." (PMID 34840814, 2021). "In summary, combination treatment with oHSV and MEKi Trametinib enhanced virus replication mediated by down-regulation of STAT1 and PKR phosphorylation in BRAF V600E-mutated tumor cells as well as BRAF wt/KRAS-mutated tumor cells." (PMID 34578339, 2021). "The RAS/BRAF mutation analysis performed on archival tumor tissue (gold standard) showed 13 false negatives and four false positives when compared to plasma analysis performed prior to the initiation of treatment." (PMID 33934494, 2021). "Nevertheless, in the univariate analysis, a higher vimentin expression was associated with the male gender, BRAF phenotype, and lymph node metastases, features linked to increased tumor aggressiveness." (PMID 34575184, 2021). "On the other hand, BRAF non-V600 mCRCs developed mainly in male and younger patients, arising more frequently from the left colon and being associated to a low tumor burden (with a single metastatic site, involving mainly the liver) and a low tumor grading." (PMID 33925278, 2021). "Most of the patients (11; 78.6%) have at least one non-BRAF mutation detected in either tumor DNA or cfDNA (or both)." (PMID 34356096, 2021). "Among 60 PTCs, 41 primary tumor tissues (68.3%) harbored the BRAF mutation, while 2 (3.5%) harbored TERT promoter mutation." (PMID 33915745, 2021).
tumor (continued). "In PTC, reduced nuclear localization of TTF-1 is linked to vascular invasion and nodal metastases and is a strong predictor of tumor recurrence in the presence of BRAF mutation." (PMID 33578751, 2021). "The gene BRAF is the only member of the RAF gene family to be frequently activated by mutations in human neoplasms." (PMID 35048058, 2021). "Low AREG and EREG mRNA levels in mCRC tumor tissues are associated with BRAF mutations and correlated with shorter OS in patients with cancer-receiving oxaliplatin/fluoropyrimidine and bevacizumab as combinational treatment." (PMID 34884633, 2021). "In PTC with tumor size > 1 cm, it has been shown that when more than 30% of BRAF V600E is present there is an association with disease aggressiveness and poorer outcome." (PMID 34135377, 2021). "This adds to the complexity of the formation of the KIAA1549-BRAF fusion within this tumour which also has 1 copy loss of the 7q arm where the KIAA1549 and BRAF genes reside." (PMID 34493325, 2021). "BRAF mutation is known to be prevalent in tumours of the proximal colon and tumours with poor differentiation (grade 3 or 4), mucinous histology, and high microsatellite instability." (PMID 33737597, 2021). "Historically, the presence of a BRAF V600 mutation was associated with more aggressive tumor features and a shorter survival." (PMID 34572865, 2021). "For the analysis of primary tumor location and BRAF V600E mutation, further studies in larger cohorts are warranted." (PMID 33744811, 2021). "Compared with BRAF wt tumor cells, the oHSV infected tumor cells harboring BRAF V600E mutations exhibited increased cytotoxicity when pretreated with Trametinib." (PMID 34578339, 2021). "We currently devise therapies for mCRC patients based on symptoms, primary tumor site, previous treatments, cancer stage, molecular evaluation (BRAF, KRAS or NRAS mutations and microsatellite instability), comorbidities, and treatment goals." (PMID 33809053, 2021). "But it was unclear how IMA tumor cells that developed from a mutation in the BRAF gene are affected by this loss in NKX2-1, and how transitioning to a different cell type impacts their response to treatment." (PMID 33821796, 2021). "Consistently with previous studies, MSI CRCs were associated with female sex, proximal tumor sites, poorly differentiated tumors, and BRAF mutation." (PMID 35047001, 2021). "Others such as ROS1 rearrangement, RET fusion, HER2 mutation, NTRK1 fusion, and BRAF V600E mutation were detected in 7.9% of CSF and 11.1% of tumor tissues but only 4% in plasma." (PMID 34671549, 2021). "KRAS mutations were found in 50% of the parental tumours (N = 8/16), BRAF V600E was present in 7% (N = 1/15) and MSI in 20% (N = 3/15)." (PMID 34572922, 2021). "In this study, MEKi Trametinib, an FDA-approved kinase inhibitor indicated for tumor treatment with BRAF V600E or V600K mutations was used as an antitumor agent to combine with oHSV T1012G." (PMID 34578339, 2021). "The BRAF V600E allele is a useful prognostic marker determining tumor malignancy, especially in countries with a high prevalence of this genetic aberration." (PMID 34769260, 2021). "Mutational heterogeneity that has been found in primary PTCs as well as in lymph node metastases is most likely not of importance because ultrasound cannot help in identifying BRAF V600E‐mutation positive regions of a tumor." (PMID 34156770, 2021).
tumor (continued). "Similar findings of PDPK1 promoting tumor initiation in cooperation with Erbb2 or Ras activation have been made in breast cancer cells, or in BRAF V600 mutant melanoma where loss of PDPK1 reduced tumor formation." (PMID 34079928, 2021). "In these latter, BRAF targeting compounds have been demonstrated to reduce tumor growth, showing efficacy in a fraction of BRAF-mutated PTC and ATC." (PMID 34072194, 2021). "Previously, among MLH1me+ dMMR CRCs, RTK-RAS activation was generally considered to be mediated by BRAF oncogenic mutation, occurring at the early stage of serrated neoplasia pathway." (PMID 34657620, 2021). "In our study, right-sided colon NEC was the only primary tumour site with a high number of BRAF V600E (70%) mutations." (PMID 34647903, 2021). "V-raf murine sarcoma viral oncogene homolog B1 (BRAF) mutations play roles in tumor cell proliferation and differentiation." (PMID 35002954, 2021). "A remarkably synergistic therapeutic efficacy was shown in vivo for BRAF wt/KRAS-mutated tumor models, when a combination of oHSV including PD-1 blockade and MEK inhibition." (PMID 34578339, 2021). "KRAS and BRAF non-V600E mutations are more frequent in smokers and have been reported as correlated with an immunogenic tumor microenvironment." (PMID 34359727, 2021). "Altogether, these results point to a significantly increased abundance of cytoplasmic p-NPM1 (Thr199) in tumor tissues from BRAF-mutated in comparison with wild-type BRAF CA patients." (PMID 34201061, 2021). "BRAF mutations and BRAF-i are also influencing the tumor microenvironment: BRAF V600E mutation promotes stromal-cell-mediated immunosuppression via IL-1 induction." (PMID 35008245, 2021). "Since 2002, BRAF pathogenic mutations frequencies and their implications have been studied in a wide variety of tumor types wherein the majority specifically involve the BRAF p.V600E mutation." (PMID 35048058, 2021). "A pathogenic BRAF mutation (c.1799T > A, p.V600E) and copy number gain (2 + 1) was also detected in the tumor and derived cell line." (PMID 33707600, 2021). "The study shows that the persistent detection of elevated copy number BRAF V600-mutated circulating tumor DNA (ctDNA) after 2 weeks of therapy correlates with a worse prognosis." (PMID 34136385, 2021). "Collectively, it suggested that pretreatment with MEKi Trametinib in BRAF V600E-mutated tumor cells facilitated oHSV replication and augmented virus oncolytic activity." (PMID 34578339, 2021). "Natural Killer (NK) cells obtained from umbilical cords of preclinical mouse models demonstrated positive outcomes in RAS and BRAF mutated neoplasms as well as Cetuximab-resistant ones." (PMID 32090113, 2020). "We compared the BRAF-mutated ctDNA concentrations in 11 dogs with the BRAF mutation with different tumor stages." (PMID 32330187, 2020). "Although this drug initially caused similar inhibition of tumor cell proliferation comparing parental and TR cells, only TR cells resisted prolonged BRAF inhibition." (PMID 32770055, 2020). "As expected, resistance to regorafenib was predictable for the presence of BRAF mutation in the tumor." (PMID 32054005, 2020). "We observed an 84.4% chance of progressive disease under ICI (p = 0.0002) for cases where the tumor harbors a mutation in one of these genes, or the patient was pretreated with BRAF/MEKi." (PMID 32825510, 2020). "In another series of 28 brainstem GG, the BRAF V600E mutation was correlated with a faster tumor regrowth compared to wild type (p = 0.001) and shorter progression free survival (p = 0.012)." (PMID 32151273, 2020). "Although we included only a small number of patients, changes in plasma mutated BRAF ctDNA levels associated with tumor progression were successfully detected by our method." (PMID 32330187, 2020).